CCR7 (C-C motif chemokine receptor 7)
Diseases named in the same sentence as CCR7 in open-access papers (continued):
Sharing a sentence is not in itself a finding about the gene and the disease.
Chlamydia (1 paper, 2019). "Moreover, Chlamydia is present in MLNs of CCR7-/- mice only at 14 dpi and the frequency of Chlamydia MLN infection and MLN titers are lower compared to the frequency of infection and titers in the spleen." (PMID 31790512, 2019).
Chlamydia infection (1 paper, 2019). "Although signaling cues that direct DC egress from the FRT during Chlamydia infection have not been previously examined, CCR7 signaling is a critical mediator of DC migration from the skin, intestinal mucosa and the lungs." (PMID 31790512, 2019).
chronic kidney disease (1 paper, 2015). Impairment of the renal function secondary to chronic kidney damage persisting for three or more months. "The study aimed at flow cytometric analysis of T cell subsets with selected surface chemokine receptors (CCR4, CCR5, CCR7, CXCR3, and CXCR4) or receptor combination in peripheral blood of children with chronic kidney disease (CKD) on hemodialysis (HD)." (PMID 25866451, 2015).
chronic leukemia (1 paper, 2022). A slowly progressing leukemia characterized by a clonal (malignant) proliferation of maturing and mature myeloid cells or mature lymphocytes. "In addition to acute leukemias, chronic leukemia progression has also been linked to CCR7 expression." (PMID 35203305, 2022).
co-infection (1 paper, 2020). "Neither the modulation of CCR7 nor α4β7 on MAIT cells were evaluated in this study, but should be explored in future experiments in the SIV/Mtb co-infection model." (PMID 32433713, 2020).
colorectal adenocarcinoma (1 paper, 2021). The most common type of colorectal carcinoma. "Various studies have shown that elevated levels of CCL21/CCR7 lead to migration and proliferation of cancerous cells, although decreased expression of CCL21 was reported in human colorectal adenocarcinoma." (PMID 33829064, 2021).
colorectal adenoma (1 paper, 2012). An adenoma that arises from the colon or rectum. "Indeed, several recent studies of colorectal adenoma tissues report reduced RNA or protein expression levels of CCR7 or its ligands, compared to surrounding normal tissues." (PMID 23055828, 2012).
coronary atherosclerosis (1 paper, 2021). Atherosclerosis of the coronary vasculature. "CCR7 knockout can inhibit the formation of atherosclerotic plaque in mice, while it significantly increases in patients with carotid and coronary atherosclerosis, to promote monocyte adhesion and migration." (PMID 33777109, 2021).
cystitis (1 paper, 2024). Inflammation of the urinary bladder. "The signalling receptor CCR7 provides deep insight into the molecular mechanisms of ageing bladder and facilitates the discovery of novel biomarkers for cystitis and BLCA treatment." (PMID 38762550, 2024).
ductal carcinoma (1 paper, 2021). "CCR7 staining in ductal carcinoma was mainly present in the cytoplasm and cell surface, particularly around the ducts, whilst in lobular carcinoma staining was mostly cytoplasmic but was also present in the nucleus of most infiltrating cells." (PMID 34298676, 2021).
Dysmenorrhea (1 paper, 2022). Pain during menstruation that interferes with daily activities. "Patients with severe dysmenorrhea also had a decreased number of CD4+ CCR7+ cells (p = 0.022)." (PMID 35576870, 2022).
eczema (1 paper, 2021). "Even variants with an imputation quality r2 < 0.8 confirmed association results at known eczema loci (FLG, ARRCD1, CCR7/SMARCE1)." (PMID 34785669, 2021).
eosinophilic pneumonia (1 paper, 2021). An inflammatory lung disorder characterized by an increased number of eosinophils in the lungs. "CCR7 and its ligands are mainly involved in the homing of T cell subsets and antigen-presenting dendritic cells to lymph nodes, and a previous study shows that dendritic cells and macrophages play a critical role in the inflammation of eosinophilic pneumonia." (PMID 34484417, 2021).
erythroderma (1 paper, 2021). "Taken together, disease exacerbation was associated with increased type-2 responses in both patients, while initial overexpression of CCR7 preceded erythroderma, but not tumor formation." (PMID 34583709, 2021).
food allergy (1 paper, 2021). Gastrointestinal disturbances, skin eruptions, or shock due to allergic reactions to allergens in food. "Here, our results show the association between DNAm levels with food allergy for CXCL12, CCR7, RUNX1, and CD3E." (PMID 33571165, 2021).
fungal infection (1 paper, 2017). "This would be consistent with a previous report where CCR7−/− DC accumulated in lung during fungal infection and promoted enhanced immunity and fungal clearance." (PMID 28216674, 2017).
glomerulosclerosis (1 paper, 2021). A hardening of the kidney glomerulus caused by scarring of the blood vessels. "The chemokine CCL21 secreted by podocytes interacts with CCR7 on mesangial cells to regulate mesangial cell proliferation and migration, and podocyte-derived PDGF similarly mediates mesangial cell proliferation and glomerulosclerosis." (PMID 34369383, 2021).
gout (1 paper, 2023). A condition characterized by painful swelling of the joints, which is caused by deposition of urate crystals. "Our analysis revealed some trends in the expression of homing receptors CCR5 and CCR7 as well as CD38 on CD4 T cells in gout patients indicating that the migratory pattern of T cells can be affected." (PMID 37714974, 2023). "Increased frequency of CCR5+ CD4 T cells and reduced numbers of CCR7+ CD4 T cells in gout suggests an enhanced recruitment of these cells to inflamed tissues." (PMID 37714974, 2023). "We observed increased numbers of CCR5-expressing CD4 T cells and reduced numbers of CCR7-expressing CD4 and CD8 T cells in gout patients." (PMID 37714974, 2023).
Hashimoto thyroiditis (1 paper, 2025). An autoimmune disorder caused by the production of autoantibodies against thyroid tissue. "In the present study, we explored the associations of serum CCL21 and CCR7 levels with the risk of Hashimoto’s thyroiditis and evaluated differences in the expression of serum CCL21 and CCR7 in patients with different thyroid antibodies and thyroid function status." (PMID 41234223, 2025). "We found that serum CCR7 levels were significantly lower in overweight patients with Hashimoto’s thyroiditis than in those with normal weight." (PMID 41234223, 2025). "Our study indicated that serum CCL21 and CCR7 levels were significantly higher in patients with Hashimoto’s thyroiditis than in healthy individuals." (PMID 41234223, 2025). "In the future, we will continue to further investigate the roles of CCL21 and CCR7 in Hashimoto’s thyroiditis." (PMID 41234223, 2025). "Further investigation is warranted to elucidate the role of the CCL21/CCR7 axis in the pathogenesis of Hashimoto’s thyroiditis and evaluate its therapeutic potential as a novel treatment target." (PMID 41234223, 2025). "Comparison of thyroid function with serum CCL21, CCR7, and other clinical parameters in Hashimoto’s thyroiditis patients." (PMID 41234223, 2025). "Studies investigating the chemokine CCL21 and its receptor CCR7 in patients with Hashimoto’s thyroiditis are scarce in the literature." (PMID 41234223, 2025). "We hypothesized that in patients with Hashimoto’s thyroiditis who are overweight or obese, this superimposed inflammation may modulate the CCL21/CCR7 axis—a signaling pathway implicated in immune cell migration and inflammatory responses." (PMID 41234223, 2025). "Further studies are needed to investigate the expression of CRR7 in lymphocyte subsets in patients with Hashimoto’s thyroiditis and the mechanisms and signaling pathways by which CCL21 mediates CCR7 to promote lymphocyte migration." (PMID 41234223, 2025).
Hernia (1 paper, 2020). "CCR7+ vessels were analyzed as a marker of inflammation within the hernia." (PMID 32138314, 2020).
Hypercholesterolemia (1 paper, 2021). An increased concentration of cholesterol in the blood. "Hypercholesterolemia, however, suppresses emigration signals via CCR7 and macrophage migratory capacity, leading to a continuous accumulation of macrophages and increased local cell death with the development of a necrotic core." (PMID 34759917, 2021). "Hypercholesterolemia blunts the CCR7-guided emigration via the expression of neuroimmune guidance cues, including netrin 1 and semaphoring 3E, and by increasing plasma membrane cholesterol content which affects intracellular signalling as well as other mechanisms." (PMID 34759917, 2021). "Not surprisingly, the reversal of hypercholesterolemia has been shown to induce CCR7 expression in plaque macrophages and with it their efflux via afferent lymphatics." (PMID 34759917, 2021).
hyperuricemia (1 paper, 2024). An abnormally high level of uric acid. "In an animal experiment, which also used potassium oxonate to induce hyperuricemia, CCR7 mRNA expression was reduced in the colon of rats after successful modeling." (PMID 39684678, 2024).
inclusion body myositis (1 paper, 2019). A slowly progressive degenerative inflammatory disorder of skeletal muscles characterized by late onset weakness of specific muscles and distinctive histopathological features. "It has been reported that the CCL19/CCR7 chemokine system is expressed in inflamed muscles of polymyositis and inclusion body myositis (IBM) and may be involved in the pathogenesis of polymyositis and IBM." (PMID 31068931, 2019).
inflammatory skin disorders (1 paper, 2024). "Other genes, such as IL-21R, GSDMC, CCR7, TLR9, HAS1/3, IL-17A, IL-22, and CXCL10, have been previously identified as genes associated with various inflammatory skin disorders." (PMID 38612783, 2024).
injury (1 paper, 2020). Damage inflicted on the body as the direct or indirect result of an external force, with or without disruption of structural continuity. "Studies have shown that the relative mRNA expression of CCR7 in peripheral blood of patients with traumatic brain injury within 24 h after onset was significantly reduced, compared with the normal control group, which was consistent with our experimental results." (PMID 32746852, 2020).
Kawasaki disease (1 paper, 2021). A rare inflammatory disease characterized by an acute febrile, systemic, self-limiting, medium-vessel vasculitis primarily affecting children. "Our study shows that we can distinguish normal samples from Kawasaki disease samples based on the infiltration of immune cells, and that CXCL8, CCL5, CCR7, CXCR3, and CCR1 may play important roles in the development of Kawasaki disease." (PMID 33188570, 2021).
kidney transplant (1 paper, 2018). A surgical procedure in which one or both kidneys from a donor are implanted into a recipient. "The regulatory function of CCR7+CD8+ T cells against effector T-cells involved in T-cell mediated rejection (TCMR) in kidney transplant recipients was investigated." (PMID 29891963, 2018).
Klebsiella pneumonia (1 paper, 2013). An pneumonia caused by infection with Klebsiella. "However, analysis of CCR7 migrating DC in the draining MLN during infection additionally indicated decreased MHC-class II expression suggesting Klebsiella pneumonia-mediated suppression." (PMID 24044871, 2013).
latent infection (1 paper, 2011). "We recently described that HIV latent infection can be established in vitro following incubation of resting CD4+ T-cells with chemokines that bind to CCR7." (PMID 21992606, 2011). "We have previously demonstrated that latent infection can be established in resting memory CD4+ T-cells in vitro following incubation with the chemokines CCL19 and CCL21 (ligands for CCR7), CXCL9 and CXCL10 (ligands for CXCR3) and CCL20 (ligand for CCR6)." (PMID 21992606, 2011).
latent syphilis (1 paper, 2023). A stage of syphilis characterized by the serologic evidence of infection by Treponema pallidum without evidence of accompanying signs or symptoms related to the disease. "Importantly, only the percentage of CD45RO+CCR7− effector memory Tfh cells to total Tfh cells was significantly different among HCs secondary syphilis and latent syphilis patients, indicating an association between these effector memory Tfh subsets and the clinical presentation of latent syphilis." (PMID 37901207, 2023).
lentivirus infection (1 paper, 2014). Virus diseases caused by the Lentivirus genus. "Since murine MSCs and human MSCs scarcely express CCR7 at the mRNA level and cell surface protein level, we introduce CCR7 gene into murine MSCs by lentivirus infection." (PMID 25549354, 2014).
leprosy (1 paper, 2025). Leprosy is a chronic infectious disease affecting primarily the skin and peripheral nervous system. "Contacts of patients with leprosy are mainly associated with CXCR3/CCR4/HLA-DR and LL/BL patients with %B-06 (IgD+) and CCR6/CCR7." (PMID 40683203, 2025).
leukoplakia (1 paper, 2021). A white patch or plaque on a mucous membrane that cannot be characterized clinically or pathologically as any other disease. "In addition, CYLD, CARD11, TCF7, CCR7, KLRB1, CD28, and ICOS were other significantly highly expressed genes among the proliferative leukoplakia subgroup (log2 fold changes, 0.65–3.51; all Padj = 0.001)." (PMID 36860910, 2021).
liver cirrhosis (1 paper, 2025). "Among them, CCR7, CXCL12, CXCR4, and CXCL8 were observed to have significantly elevated expression in liver cirrhosis samples." (PMID 41223189, 2025).
lobular carcinoma (1 paper, 2021). "The expression of chemokine receptor CCR7 was assessed in patient samples with invasive ductal and lobular carcinoma with and without lymph node involvement using immunohistochemistry." (PMID 34298676, 2021).
low grade glioma (1 paper, 2023). A grade I or grade II glioma arising from the central nervous system. "We observed increased CCR7 expression in GBM compared with all other low-grade glioma (LGG) subtypes." (PMID 37314567, 2023).
lupus nephritis (1 paper, 2015). Glomerulonephritis in the context of systemic lupus erythematosus. "Chemokines and chemokine receptors are used as therapeutic targets in lupus nephritis; therefore, we assessed the surface expression of the most important chemokine receptors (CCR6, CCR7, CXCR4 and CXCR5) on B lymphocytes from all four groups by flow cytometry." (PMID 25909640, 2015).
MALT lymphoma (1 paper, 2021). An indolent, extranodal type of non-Hodgkin lymphoma composed of small B-lymphocytes (centrocyte-like cells). "In extragastric MALT lymphoma or malignant transformation from Helycobacter pylori-associated gastritis to MALT lymphoma, up-regulation of CCR7 mRNA, among other CKRs, was a common finding." (PMID 34778050, 2021).
medulloblastoma (1 paper, 2015). A malignant, invasive embryonal neoplasm arising from the cerebellum. "When hAT-MSCs were co-cultured with medulloblastoma-BTICs, the expression levels of CCR4, CCR5, CCR7, XCR1, CXCR1, CXCR4, PDGFR-bb, KDR and TEK were increased, while the levels of CX3CR1, IL1R, IL6R, IL8R, IGF1R and CD44 were decreased (p<0.05)." (PMID 26076490, 2015).
metastatic squamous cell carcinoma (1 paper, 2015). A squamous cell carcinoma which has spread from its original site of growth to another anatomic site. "First, a previous study demonstrated that these two transcription factors are important for in the regulation of CCR7 expression in metastatic squamous cell carcinoma of head and neck." (PMID 25557171, 2015).
migraine (1 paper, 2018). "The microarray analysis implicated thyroid hormone receptor beta which had been previously associated with migraine, and chemokine signalling (Ccr7), among many others as well as long non-coding RNAs (lncRNA) putatively involved in gene regulation." (PMID 29997476, 2018).
myeloid neoplasm (1 paper, 2021). Proliferation of myeloid cells originating from a primitive stem cell. "In this section we will appraise the current knowledge on CCR7 biology in several B-cell and T-cell cancers and in selected myeloid neoplasms." (PMID 34778050, 2021). "Description of CCR7 in myeloid-cell derived cancers is anecdotal and, as opposed to lymphoid disorders, myeloid neoplasms seem to be mainly characterized by downregulated CCR7, although this aspect still remains controversial." (PMID 34778050, 2021).
myocarditis (1 paper, 2012). Myocarditis is a condition that is characterized by inflammation of the heart muscle (myocardium). "CXCL9 mRNA expression directly correlated with the intensity of myocarditis, as well as with mRNA expression of CXCR3, CCR4, CCR5, CCR7, CCR8 and their ligands." (PMID 23150742, 2012).
nasopharyngeal carcinoma (1 paper, 2022). A carcinoma arising from the nasopharyngeal epithelium. "Serum levels of CCR7 appeared to be a relevant marker for patients with locally advanced nasopharyngeal cancer since a higher concentration of CCR7 was a good predictor for a locally advanced tumor and poor prognosis." (PMID 35203305, 2022).
non-melanoma skin carcinoma (1 paper, 2022). "This distribution did not exist in non-melanoma skin cancer with no metastatic potential, basal cell carcinoma, or actinic keratosis, when compared with normal skin, suggesting a possible role for CCR7 in non-melanoma skin cancer metastasis." (PMID 35203305, 2022).
pancreatic adenocarcinoma (1 paper, 2022). "Stimulation of the CCR7-expressing pancreatic adenocarcinoma-derived cell line, PANC1, with CCL19 led to enhanced expression of p-ERK, p-AKT, N-cadherin and MMP-9, markers of EMT progression, further implicating CCR7 in the metastatic progression of pancreatic adenocarcinomas." (PMID 35203305, 2022). "CCR7/CCL21 activation and its role in EMT using different pancreatic adenocarcinoma cell lines and resected tissue were investigated." (PMID 35203305, 2022).
papillary thyroid cancer (1 paper, 2022). "A study of 30 patient samples of papillary thyroid cancer found that CCR7 was infrequently detected with 5–10% of cells being CCR7 positive." (PMID 35203305, 2022). "Immunohistochemical analysis of 88 papillary thyroid cancer specimens from 65 patients showed that samples having extrathyroidal extensions, angiolymphatic invasion or lymph node metastasis had elevated staining for CCR7 compared with those without the invasive characteristics." (PMID 35203305, 2022).
Parkinson disease (1 paper, 2021). A progressive degenerative disorder of the central nervous system characterized by loss of dopamine producing neurons in the substantia nigra and the presence of Lewy bodies in the substantia nigra and locus coeruleus. "However, the TEMRA population was defined differently (CD8+CD45RA+CD27−, as opposed to CD8+CD45RA+CCR7−); furthermore, T cell immunosenescence may play differing roles in Alzheimer’s and Parkinson’s diseases." (PMID 34645462, 2021).
pemphigus (1 paper, 2023). Pemphigus is a group of rare autoimmune diseases that cause blistering of the skin and mucous membranes (mouth, nose, throat, eyes, and genitals).This conditioncan occur at any age, but often strikes people in middle or older age. "The study demonstrated that skin‐infiltrating CD4+CD69+CCR7− Trm was more prevalent in pemphigus patients than in healthy controls and was positively correlated with the pemphigus disease area index." (PMID 36539957, 2023).
plasma cell leukemia (1 paper, 2021). An aggressive plasma cell neoplasm characterized by the presence of neoplastic plasma cells in the peripheral blood. "Available evidence does not link CCR7 to an altered genetic profile in plasma cell leukemia (PCL)." (PMID 34778050, 2021).
Pleural effusion (1 paper, 2021). The presence of an excessive amount of fluid in the pleural cavity. "In most of these studies, MCL cells from LN, PB, BM, and pleural effusions expressed higher levels of CCR7 than their proposed normal counterparts." (PMID 34778050, 2021). "Normal plasma cells and those of MM do not typically express surface CCR7, and if expressed, it is found in a minor proportion of cells as demonstrated in samples from BM or extramedullary sites (PB and pleural effusions)." (PMID 34778050, 2021).